ICAM1 (intercellular adhesion molecule 1)
Diseases named in the same sentence as ICAM1 in open-access papers (continued):
Sharing a sentence is not in itself a finding about the gene and the disease.
endometriosis (39 papers, 2012 to 2026). The growth of functional endometrial tissue in anatomic sites outside the uterine body. "Increasing evidence points to a crucial role for ICAM-1 in the pathological processes underlying endometriosis." (PMID 27790149, 2016). "ICAM1 is linked to endometriosis-associated inflammation and infertility." (PMID 41227338, 2025). "Other serum biomarkers, including glycoproteins like intercellular adhesion molecule-1 (ICAM-1), are being developed alongside genomic approaches to facilitate the diagnosis of endometriosis and predict its severity." (PMID 41517625, 2026). "APOE was associated with 17 drugs for treating endometriosis, ICAM1 with 5 drugs, and MME with 8 drugs for treating endometriosis." (PMID 39650066, 2024). "The defective expression of ICAM-1 (CD54) on secretory endometrial cells indicates the interaction between pro-inflammatory and anti-inflammatory mediators in the development of endometriosis." (PMID 38337827, 2024). "NF-kB is also activated, and ICAM-1 expression in endometriosis confirms the inflammatory pattern, according to Kaabachi’s study (2017)." (PMID 38337827, 2024). "The transcriptional activity of a number of proinflammatory cytokines/chemokines, such as IL-1, IL-6, IL-8, TNF-α, RANTES, MIF and ICAM1, is activated by NFκB signaling, demonstrating the key role of NFκB in the inflammatory response in endometriosis." (PMID 36359004, 2022). "At the same time, a decreased concentration of intercellular adhesion molecule-1 (ICAM-1) was observed in the serum of endometriosis patients." (PMID 35935991, 2022). "Diverse factors, including TGF-β, TNF-α, IL-1β and IL-6 that have been shown to upregulate ICAM-1 expression in other contexts, are known to increase endometrial cell adhesion to the peritoneum in an in vitro model of endometriosis." (PMID 29772648, 2018). "Intercellular adhesion molecule-1 (ICAM-1) is involved in the pathogenetic mechanisms responsible for immune-mediated diseases including disorders of female reproductive system such as endometriosis, ovarian stimulation syndrome, and preeclampsia." (PMID 24591755, 2014). "Human ectopic endometrial stromal cells strongly express ICAM-1, and these cells express a higher level of ICAM-1 than eutopic endometrial stromal cells in patients with endometriosis." (PMID 23843796, 2013). "In the case of endometriosis, greater amounts of ICAM-1 are released by the ectopic endometrium and by the endometriosis implants and found to be significantly higher serum concentrations (nv : 410.4 ng/mL) compared with controls." (PMID 23093966, 2012). "CA 125, Ca 19.9, ICAM-1, and IL-6 together with follistatin and urocortin have proven to be the most reliable markers for endometriosis diagnosis." (PMID 23093966, 2012). "Notably, miR-146a-5p suppressed ICAM1, a gene overexpressed in endometriosis that promotes leukocyte infiltration and tissue damage." (PMID 41227338, 2025). "Research indicates that ICAM1 can serve as a biomarker for endometriosis." (PMID 39650066, 2024). "Other studies defined increase and pathogenic role of this cytokine in peritoneal fluid and eutopic endometrium of participant with endometriosis through increase inflammation and up-regulate the expression of sICAM-1 in eutopic endometrium and interfere with immune function by ICAM-1, respectively." (PMID 38868448, 2023). "Serum ICAM-1 levels were higher in endometriosis patients compared to healthy women." (PMID 35246120, 2022). "ICAM-1 alone or together with soluble vascular cell adhesion molecule 1 (VCAM-1) may be a promising biomarker for diagnosing endometriosis." (PMID 35935991, 2022). "The expression of CD44 and ICAM-1 in ectopic endometrial cells may promote adhesion and enhance endometriosis pathogenesis." (PMID 33807420, 2021). "Another important mediator involved in the pathological development of the endometriosis is ICAM-1." (PMID 30140375, 2018).
endometriosis (continued). "Furthermore, the inhibition of NF-κB in an animal model of endometriosis reduced ICAM-1 expression and cell proliferation, with endometriotic lesions concurrently undergoing increased apoptosis." (PMID 29772648, 2018). "ICAM-1 is involved in the impairment of NK cell function in endometriosis." (PMID 23843796, 2013). "In some studies, the changes in ICAM-1 mRNA and sICAM-1 levels were observed even before visible disease, suggesting that ICAM-1 may be involved in the very early pathogenesis of endometriosis as well as its later propagation and deleterious downstream effects." (PMID 29772648, 2018). "This picture is consistent with our findings, specifically the overexpression of ICAM1 and VCAM1, particularly in deep infiltrating endometriosis tissue and in peritoneal lesions (PeL) or eutopic endometrium (PE) of ES patients." (PMID 40747097, 2025). "There are other components of innate immunity, including TNF-α, IL-1β, IL-6, IL-17A, ICAM-1/LFA-1, and HMGB-1, that participate in the pathogenesis of endometriosis." (PMID 36865552, 2023). "Our results provide further insights regarding the ability of ALA to inhibit endometriotic cellular ICAM-1-mediated adhesion and MMP-mediated cellular invasion, suggesting a role on the inhibition of endometriosis progression." (PMID 33430114, 2021). "The levels of angiogenin, CD105, ICAM-1, CXCL10, leptin, lipocalin-2, MMP-9, osteopontin, RBP4, PAI-1, ABP, CD31, TIM-2, and VCAM-1 were higher in the endometriosis group than in the control group." (PMID 34072419, 2021). "Some of them, such as Rap1 pathway and leukocyte transendothelial migration pathway(including Intercellular Adhesion Molecule 1[ICAM-1) and Integrin Subunit Alpha L (ITGAL)], have been proven as involved in endometriosis." (PMID 34122342, 2021). "Intercellular adhesion molecule-1 (ICAM-1) is a glycoprotein that seems to be involved in the development and promotion of endometriosis." (PMID 32143439, 2020). "The expression of cell adhesion molecules such as ICAM-1 and VCAM-1 plays a vital role in the development of endometriosis, especially in the early stages of pathogenesis." (PMID 31636643, 2019). "Moreover, in endometriosis, the expression changes of VCAM-1 and ICAM-1 play a crucial role, and the ratio of soluble VCAM-1 to soluble ICAM-1 may serve as a potential biomarker." (PMID 38660311, 2024). "Furthermore, the levels of cell adhesion molecules such as ICAM-1, VCAM-1, and CD44, which modulate cell–matrix and cell–cell attachments, are increased in the serum, peritoneal fluid, and endometrium of patients with endometriosis." (PMID 35409294, 2022). "In addition to these two biomarkers, there are also a number of proteins related to tissue inflammation, including IL-1, IL-6, IL-8, TNF-alpha, ICAM-1, MMPs, TIMPs, or VEGF, that may prove useful for endometriosis detection." (PMID 35453583, 2022). "Furthermore, Eleng capsules may also lower serum levels of soluble intercellular adhesion molecule-1(sICAM-1) and MMP-9 in patients with endometriosis, suggesting effects upon cell adhesion, invasion and angiogenesis." (PMID 30402122, 2018).
hepatocellular carcinoma (39 papers, 2007 to 2026). A malignant tumor that arises from hepatocytes. "In a model of hepatocellular carcinoma, ICAM-1 was associated with increased vascular permeability through the VE-cadherin dependent interaction with endothelial cells." (PMID 40071851, 2025). "ICAM-1 is an adhesion molecule highly expressed in chronic hepatitis B infection and found to be associated with hepatocellular carcinoma." (PMID 35216324, 2022). "Intercellular adhesion molecule (ICAM-1) is highly expressed in chronic hepatitis B infection and is associated with hepatocellular carcinoma." (PMID 35216324, 2022). "The soluble fraction of ICAM-1 in the blood of hepatocellular carcinoma patients correlated positively with a better OS and a lower recurrence rate but was also predictive of a poor response to immune checkpoint inhibition." (PMID 40071851, 2025). "In conclusion, our findings have revealed that CXCL1 downregulates the expression of miR-30b-5p, leading to increased expression of ICAM-1, thereby promoting the motility of hepatocellular carcinoma cells." (PMID 39132161, 2024). "This study focused on the role of microRNAs in CXCL1-mediated ICAM-1 expression and cell motility in human hepatocellular carcinoma." (PMID 39132161, 2024). "These outcomes emphasize the critical function of ICAM-1 in the metastatic progression of hepatocellular carcinoma facilitated by CXCL1." (PMID 39132161, 2024). "ICR was firstly identified to regulate ICAM-1 expression and promote hepatocellular carcinoma metastasis by binding to ICAM-1 mRNA and increasing its stability." (PMID 35688937, 2022). "Previous reports also showed NANOG-mediated ICAM1 expression regulation in hepatocellular carcinoma, however, ICAM1 was conversely upregulated by NANOG therein." (PMID 31619256, 2019). "However, identifying the precise microRNA responsible for regulating ICAM-1 in the migration of hepatocellular carcinoma cells remains a challenge." (PMID 39132161, 2024). "Furthermore, ICAM-1-positive hepatoma cells had a better ability of generating tumors when injected to nude mice." (PMID 38786066, 2024). "SCARB2-expressing hepatocellular carcinoma cells or ICAM-1-positive triple-negative breast cancer cells could be targeted by EV71 or Coxsackievirus A, while PVR-expressing glioblastomas could be targeted by polioviruses." (PMID 39335111, 2024). "ICAM-1 correlates with hepatoma tumor stemness and is required for tumor metastasis." (PMID 38786066, 2024). "Furthermore, the miR-30b-5p mimic significantly suppressed CXCL1-promoted ICAM-1 production and cell migration in hepatocellular carcinoma cells." (PMID 39132161, 2024). "Kaplan-Meier analysis revealed worse overall survival rates in the high CXCL1 expression group, suggesting its potential as a biomarker for cancer progression and stimulating hepatocellular carcinoma cells with CXCL1 enhanced migration abilities by upregulating ICAM-1 expression." (PMID 39132161, 2024). "In this study, we obtained that oleanolic acid promotes high expression of HMOX1, PIM1 and ICAM1 in hepatocellular carcinoma cells through oleanolic acid-related expression profiles, which further suggests that HMOX1, PIM1 and ICAM1 are key targets of oleanolic acid." (PMID 38127054, 2023). "Importantly, ICAM-1 from HepG2 cells colocalized with cells positive for the macrophage marker F4/80 (boxed area 1), suggesting that hepatoma cells interact with immune cells infiltrated in the tumor." (PMID 34999972, 2022). "Using a mouse liver carcinoma model, it has been demonstrated, that senescent tumor cells induced innate immune response due to their inflammatory cytokine secretion, accompanied by increase of leukocyte attracting molecules like ICAM1 or VCAM1." (PMID 27448982, 2016). "Recently, ICAM1 was identified to serve as a marker of hepatocellular carcinoma stem cells." (PMID 26571024, 2015).
hepatocellular carcinoma (continued). "The database contains longitudinal liver MRI scans from mice with hepatocellular carcinoma, metabolic dysfunction-associated steatohepatitis (MASH, formerly NASH), and fibrosis, as well as CT scans of mice with MASH and mice carrying a dysfunctional ICAM-1 gene." (PMID 41872225, 2026). "In addition, overexpression of CXCL1 in HepG2 and HepG2/C3A cells (which have the lowest CXCL1 expression) or the knockdown of CXCL1 in Huh7 and Hep3B cells (which have the highest CXCL1 expression), respectively, promoted and reduced ICAM-1 protein expression in hepatocellular carcinoma cells." (PMID 39132161, 2024). "However, the role of CXCL1 in ICAM-1 expression and in metastasis of hepatocellular carcinoma remains unclear." (PMID 39132161, 2024). "Our research revealed that CXCL1 increases ICAM-1 levels, and the utilization of ICAM-1 siRNA diminished ICAM-1 expression and reduced the CXCL1-stimulated migration in hepatocellular carcinoma cells." (PMID 39132161, 2024). "In hepatoma cell cultures, SASP factors, including CSF1, MCP1, CXCL1 and IL‐15, as well as adhesion molecules such as Icam1 and Vcam1, have been observed to attract a spectrum of immune cell types, encompassing macrophages, NK cells and neutrophils." (PMID 39270064, 2024). "In addition, the RNA-seq data and clinical information of The Cancer Genome Atlas Liver Hepatocellular Carcinoma were collected to analyze the predictive values of AFP and ICAM-1 in the diagnosis, prognosis and immunotherapy of HCC." (PMID 34696675, 2021). "ICAM-1/LFA-1 interactions also appear to drive HIV-1 transmission from infected CD4+ T cells to trophoblasts and from human hepatoma cells to CD4+ T cells." (PMID 22970312, 2012). "For example, fucosylated APOH, CD14 and ICAM1 were detected with a high level in plasma of patients with human hepatocellular carcinoma (HCC) and fucosylated ICAM1 may represent a good prognostic marker for HCC." (PMID 34199928, 2021). "Further, human hepatocellular carcinomas (HCC) are more heavily infiltrated with T cells compared to colorectal hepatic metastases (CHM) and that the T cell infiltration was associated with higher expression of ICAM-1 and VAP-1 on tumor-associated endothelial cells in HCC." (PMID 31231358, 2019). "We found that exosomes released by CD90+Huh7 cells, and not by hepatoma cells, increased the number of HUVECs expressing ICAM-1 and, more extensively, increased the adhesion between endothelial cells and the CSC-like CD90+ cells." (PMID 26272696, 2015). "Our results revealed that insufficient RFA up-regulated the expression of E-selectin, ICAM-1 and VCAM-1 in TAECs, which suggests that up-regulated adhesion molecules may be the mechanism responsible for the enhanced adhesion of TAECs to hepatoma cells." (PMID 23171368, 2012). "However, a previous report indicated that while NANOG bound to the ICAM1 promoter region in CIC-like hepatocellular carcinoma cells, OCT4 and SOX2 did not." (PMID 31619256, 2019). "To date, the binding of human FXR in primary human hepatocytes (PHHs) or hepatoma cell lines has been characterized to limited genes, including ABCB4 (ATP-binding cassette, sub-family B, member 4), ABCB11, FGF19 (fibroblast growth factor 19), ICAM1 (intercellular adhesion molecule 1), and NR0B2." (PMID 25198545, 2014). "Moreover, our previous study showed that ICAM-1 and VCAM-1 were also expressed in hepatocellular carcinoma (HCC) and promoted HCC cell adhesion to the endothelium." (PMID 26690142, 2015).
lymphoma (37 papers, 2007 to 2025). A malignant (clonal) proliferation of B- lymphocytes or T- lymphocytes which involves the lymph nodes, bone marrow and/or extranodal sites. "Conditional knockout of the LTβR in ECs (Cdh5CreERT2xLtbrfl/fl referred to as Ltbrfl/fl) caused a reduction of PNAd, CCL21, and ICAM1 expression in BECs, similar to the dedifferentiation observed in HECs during lymphoma challenge." (PMID 34706240, 2021). "Loss of ICAM-1 after exposed lymphoma cell to rituximab may contribute to the resistance to rituximab." (PMID 33288735, 2020). "Our group has shown that treating KSHV-infected PEL or certain EBV-infected lymphoma B-cell lines with Pom leads to the upregulation of important immune surface markers including ICAM-1, B7-2, MICA, and MHC-I19." (PMID 37463943, 2023). "A lack of homing receptor molecules, such as CD29 (beta-1 integrin) and CD54 (ICAM-1), on the surface of lymphoma cells impairs their ability to exit the tissues and partially explains their peculiar intravascular location." (PMID 37958219, 2023). "The T-cell responses against the lymphomas generally tracked with the relative levels of ICAM-1 and B7-2 on the cell surface of these lines." (PMID 33411730, 2021). "ICAM1 levels additionally correlate with the metastatic stage of lymphoma dissemination and clinical stage of CLL." (PMID 32370190, 2020). "In lymphoma patients before rituximab era, several papers reported that ICAM-1 expression was found correlated to the lymphoma dissemination and had prognostic value for the treatment and survival." (PMID 33288735, 2020). "On the other hand, immunohistochemistry studies reported better prognosis for patients with ICAM1-positive tumors (including lymphoma, ovarian, colorectal, head and neck cancers)." (PMID 28105922, 2016). "Based on our data, we speculate that elevated ICAM-1 expression on lymphoma-activated FRCs could exert adhesive breaks for migrating lymphocytes." (PMID 37219943, 2023). "ICAM-1 is expressed on the surface of several types of solid malignant cells, as well as on essentially all hematopoietic cancer cells such as leukemia and lymphoma." (PMID 35911772, 2022). "This indicates an important role of ICAM1 in microenvironment interactions that could account for reports that high-grade lymphomas express higher levels of ICAM1 compared to low-grade tumors." (PMID 32370190, 2020). "Lymphoma patients with higher ICAM-1 expression had higher overall survival rate." (PMID 33288735, 2020). "Numerous serum biomarkers for lymphomas were proposed for their clinical value such as soluble intercellular adhesion molecule-1 (s-ICAM-1/s-CD54); soluble Fas/CD95/APO-1; soluble tumor necrosis factor receptor 2 (sTNF-R2); soluble interleukin-2 receptor (sIL-2R); nm23-H1 protein; and soluble CD44." (PMID 28282874, 2017). "Binding of DC-SIGN and other glycan-specific receptors to the Lewisx epitopes on CD98 and intercellular adhesion molecule-1 may facilitate interaction of the lymphoma cells with lymphocytes and myeloid cells in lymph nodes." (PMID 21435201, 2011). "In stratified analysis by tumor subtype, we did not determine any significant associations between EVs bearing PD-L1, CD40, FasL, IL-6Rα, B7-H3, CD40L, ICAM-1 or CD20 with DLBCL, BL, and NOS lymphoma subtypes." (PMID 37809067, 2023). "Both ICAM-1 and LFA-1 play critical roles in immune function and are downregulated in latency I lymphomas to assist immune evasion." (PMID 29202043, 2017). "ICAM-1 upregulation was higher for brain tumors, EWS, NB and leukemia, and lower for RMS and lymphomas." (PMID 28428785, 2017). "However, ICAM-1 upregulation exceeded MHC-class I upregulation (ratio <1) in the EWS cell lines CHLA-9 and CHLA-10 and the lymphoma cell line Ramos-RA1, for which IFNγ treatment resulted in decreased NK cell-mediated lysis." (PMID 28428785, 2017).
lymphoma (continued). "Next, assessment of integrin activation and cell adhesion showed that, in the absence of stimuli, lymphoma cells increased their adhesion to both ICAM-1- and VCAM-1-containing substrates, indicating basal activation of LFA-1 and VLA-4 integrins, respectively." (PMID 27297662, 2016). "In contrast, targeting ICAM1 did not affect lymphoma survival." (PMID 38195569, 2024). "The peculiar affinity of lymphoma cells to the intravascular space has been linked to the absence of CD29 (b1 integrin) and CD54 (ICAM‐1) surface ligands, which may disable them from diapedesis across the endothelium." (PMID 35713565, 2022). "However, in rituximab era, the prognostic value of ICAM-1 has not been known in lymphoma." (PMID 33288735, 2020). "On the other hand, the adhesion molecule ICAM-1 was upregulated by IFNγ on brain tumors, EWS, NB, and leukemia, but not on RMS and lymphoma cells." (PMID 28428785, 2017).